IL6 (interleukin 6)
Diseases named in the same sentence as IL6 in open-access papers (continued):
Sharing a sentence is not in itself a finding about the gene and the disease.
asthma (continued). "Taken together, our findings showed that RV infection induced aberrant host immune responses mediated by IFN-γ, IL-17A, and IL-6 in asthma." (PMID 36366542, 2022). "Previous studies showed that SOCE is critical for IL-6 secretion by airway epithelial cells and that the asthma-inducing allergen HDM mediates SOCE-dependent secretion of IL-6 by airway epithelial cells." (PMID 35841929, 2022). "To deepen our understanding of possible functional interaction between TNF and IL-6 in the context of allergic asthma, in the present study using a mouse model of HDM-induced asthma we examined the effects of combined IL-6 and TNF inhibition." (PMID 35408882, 2022). "Then, in the experiment of PEF against asthma, our findings showed that the expression of IgE, IL-4, IL-5, IL-6, IL-13, and IL-17 were significantly higher in the model group." (PMID 36172200, 2022). "Increased blood IL-6 is a common indicator of systemic inflammation of asthma and COPD, suggesting the therapeutic potential of IL-6 antagonists in COPD emphysema and associated complications." (PMID 35280870, 2022). "IL-1β release mediates the release of other inflammatory cytokines, including TNF-α and IL-6, which play essential roles in the pathogenesis of pulmonary diseases such as asthma, pulmonary fibrosis, and COPD." (PMID 36432032, 2022). "To determine the relationship between PRB1 and type 2‐high asthma further, we detected the levels of IL‐2, IL‐4, IL‐5, IL‐6, IL‐10, IL‐13, IL‐17, and INF‐γ in the induced sputum supernatant." (PMID 35344278, 2022). "The final cluster, which was the most saturated with cases of nasal polyps and asthma, had the highest concentration of IL-5 along with high concentrations of IL-6 and IL-8 and had the presence of s." (PMID 36285981, 2022). "Airway smooth muscle cells can also induce a proinflammatory environment in asthma by secreting a myriad of inflammatory cytokines, including a family of interleukins (IL), such as IL-1, IL-5, IL-6, and IL-8, and growth factors, including TGF-β1 and VEGF." (PMID 35888038, 2022). "Our findings suggest that there are increased IL-6 levels in nocturnal asthma resulting from inhibition of the BMAL1/FOXA2 signalling pathway in airway epithelial cells." (PMID 36505412, 2022). "Instead of T2-related cytokines, cells, such as Th1 and Th17, and downstream cytokines, such as IL-6 and IL-17, were involved in the mechanism of non-T2 asthma, leading to subsequent airway impairment." (PMID 35628903, 2022). "The formation of pathophysiological features of asthma can occur through the release of pro-inflammatory cytokines such as interleukin (IL) 1β and IL-6, while epithelium-derived IL-33 promotes Th2 differentiation." (PMID 36141448, 2022). "Studies on asthma indicate that inhibiting the production of inflammatory factors, such as IL-1, IL-6, IL-8, IL-4, IL-5, TNF-α, and IFN-γ, can reduce allergic symptoms." (PMID 36307493, 2022). "Another mechanism by which IL-6 can increase muscle mass can be by decreasing the inhibitory effect of glucocorticoid, since the role of IL-6 in experimental asthma-induced glucocorticoid insensitivity has been recently reported." (PMID 35408999, 2022). "We determined the effect of miR-155 deficiency on FcεRI-induced production of the proinflammatory cytokines TNF and IL-6, and the mucus-promoting cytokine IL-13, which plays a prominent role in asthma." (PMID 36211602, 2022). "Herein, we observed that Vit D significantly decreased expression levels of IL‐6 and IL‐17, whereas levels of the asthma‐protective factor IL‐10 were increased." (PMID 35959262, 2022). "On the other hand, in non-T2 asthma models, after epithelial injury, IL-6, TNF, and IL-1a production are stimulated, and neutrophilic inflammation is induced." (PMID 36326393, 2022). "The impact of exercise interventions on IL‐6 levels in asthma patients is inconsistent in randomized clinical trials." (PMID 35811337, 2022).
asthma (continued). "The pro-inflammatory cytokines IL-1B and IL-6, on the other hand, are reduced in Sarcoidosis exosomes, whereas asthma treatment encourages monocytes to produce pro-inflammatory cytokines and CCL2." (PMID 35928365, 2022). "The age-based and ethnicity-based subgroup analyses in asthma indicated that IL-6 rs1800795 was a protective factor against asthma in Caucasians—children and adults." (PMID 35368692, 2022). "For one unit increase of IL6 (after log transformation), the odds ratio of both asthma and wheezing was 1.28 (95% CI: 1.03–1.59, P = 0.026)." (PMID 36253437, 2022). "Administration of anti-IL-6 antibodies during asthma induction increased IL-13, IL-4, and IL-5 protein levels in the BALF." (PMID 35408882, 2022). "CSBHT is also considered to improve asthma through additional anti-inflammatory action by inhibiting pro-inflammatory cytokines such as IL-6 and IL-8." (PMID 35887796, 2022). "Older patients with asthma with elevation of IL-1β, IL-6, and MIP-3a/CCL20 levels were reported to have a greater risk of hospitalization, along with those with IL-6- and IL-23-deteriorated asthma control." (PMID 36291665, 2022). "Macrophages also play an important role in asthma, and the inflammatory factors produced by macrophages, such as IL-6, NO, and ROS, are also important markers of asthma." (PMID 35163503, 2022). "Taken together, our results provide evidence for therapeutic potential of combined IL-6/TNF inhibition in severe steroid-resistant asthma." (PMID 35408882, 2022). "During the inflammatory response, eosinophils also induce lymphocytes to synthesize and release cytokines such as IL-1β, IL-4, IL-6, and IL-13, which promote and exacerbate asthma attacks." (PMID 36408342, 2022). "Recent mouse studies, along with the surprising GWAS results demonstrating a genetic link between IL-6R and human asthma, indicated that IL-6 (or IL-6R) is a priority for asthma treatment." (PMID 35052792, 2022). "In contrast, the pathobiology of T2-low asthma typically involves Th1 and Th17 cells, neutrophils and several proinflammatory cytokines such as IL-1β, IL-6, IL-17A, IL-17F, IFN-γ and TNF-α." (PMID 34777398, 2021). "ETS variant transcription factor 4 (ETV4) is a recently identified transcription factor that regulates gene expression-based biomarkers of asthma and IL6 production in an airway epithelial cell line." (PMID 34552174, 2021). "TGFβ (transforming growth factor beta), IL-22, IL-6 and TNF also contribute to tissue remodeling and fibrosis that are associated with the late stages of asthma progression." (PMID 34084159, 2021). "Our asthma patients demonstrated significantly elevated proinflammatory cytokine levels (IL-6, TNFα and sTNF RI) compared to healthy controls." (PMID 34112152, 2021). "An increase in the levels of Th2 cytokines (IL-4, IL-5, and IL-13, among others) and Th17 cytokines (IL-17 and IL-6, among others) was observed in both patients with asthma and animal models of asthma." (PMID 34526979, 2021). "IL-6 and TNF are key pro-inflammatory cytokines implicated in neutrophilia, extracellular matrix production and chronic inflammation during severe asthma." (PMID 34084159, 2021). "HDM-induced IL-1β and IL-6 production were significantly lower in children with asthma than healthy controls (P<0.001)." (PMID 34220812, 2021). "Our paper can provide a solid theoretical basis for the clinical targeting of IL-6 in the treatment of asthma." (PMID 34402724, 2021). "Among many immune components involved in the pathobiology of asthma, recent research has suggested a potential role of interleukin-6 (IL-6) signaling—the classic and trans-signaling pathways." (PMID 33912579, 2021). "Our findings indicate that BMI was positively correlated with sTNF RI, TNF-α and IL-6 but only in younger patients with asthma, which suggests that systemic inflammation in elderly is modified by also other factors." (PMID 34112152, 2021).
asthma (continued). "Reactome ontology of genes that are overexpressed in asthma and CD linked them to the unfolded protein response (FDR = 1.00 × 10–5), activation of chaperone genes (FDR = 2.06 × 10–5), interleukin-6 (FDR = 0.008), and interferon signaling (FDR = 0.013)." (PMID 34332619, 2021). "All patients with asthma demonstrated elevated TNFα, IL-6 and sTNF RI levels compared to controls (p = 0.026, p = 0.03 and p < 0.001 respectively)." (PMID 34112152, 2021). "The vitro model of asthma treated with miRNA-221-5p mimic resulted in the reduction of IL-6, IL-17, IL-21 and IL-22 levels, and induction of IL-10, IL-35 and TGF-β levels." (PMID 34863307, 2021). "IL-6 is a cytokine that controls the pathogenesis of asthma and the early stages of development of Th2 cells, a biomarker of asthma exacerbation." (PMID 34580637, 2021). "We observed decreased mRNA expression of TSLP in asthma and decreased expression of IL-6 mRNA COPD in moMφs after the exposure to UPM." (PMID 34168212, 2021). "Study has found that asthma was more severe in patients with excessive cytokine expression, such as IL6, IL1B, and TNF-α." (PMID 34221070, 2021). "The importance of this cytokine in severe asthma will need confirmation by trials inhibiting IL-6 signalling." (PMID 35055325, 2021). "Asthma occurs accompanied by the ferroptosis in bronchial epithelial cells, during which Interleukin-6 (IL-6) plays a key role." (PMID 34402724, 2021). "IL‐6 is secreted from epithelial cells in respiratory virus infection and induces airway inflammation and bronchospasms in patients with asthma and upper respiratory tract infections." (PMID 33470564, 2021). "IL-6 inhibitors were considered to ameliorate metabolic dysfunction in much severe asthma, indicating the positive correlation of IL-6 with clinical presentations of metabolic dysfunction in this disease." (PMID 34608825, 2021). "In this paper, we discuss the role of IL-6 in asthma and its mechanism of action on ferroptosis of bronchial epithelial cells." (PMID 34402724, 2021). "It is interesting that numerous changes in the mRNA expression for IL-6 or IL-8 were more frequently observed in the control group than in asthma or COPD." (PMID 34168212, 2021). "IL-6, released by macrophages in the adipose tissue, is a cytokine that has recently gained attention as a key player in non-T2 asthma." (PMID 35055325, 2021). "The results showed that the levels of IL-6, IL-8, and IL-33 were markedly increased in serum of patients with asthma in comparison with that of healthy subjects (p < 0.01)." (PMID 33506046, 2021). "IL-6 is a cytokine that is activated and secreted by lymphocytes and mononuclear macrophages and has an important impact on the development of asthma." (PMID 34880921, 2021). "Th17 cells also produce other pro-inflammatory cytokines such as IL-6 and tumor necrosis factor-α, which play trivial roles in the inflammatory cascade stimulated in the state of asthma." (PMID 33980319, 2021). "Patients with asthma had significantly higher levels of IL-1β (19.74±16.77 vs. 2.63±5.22 pg/mL), IL-6 (7.55±8.65 vs. 2.37±2.47 pg/mL), and TNF-α (12.70±12.03 vs. 4.82±3.97 pg/mL) than the controls." (PMID 33503170, 2021). "Evaluating the effect of black cumin on asthma-related inflammatory mediators, Koshak and the team reported that the oily TQ-rich extract promoted immune response by reducing IL-2, IL-6, and PGE2 in primary T-lymphocytes and IL-6 and PGE2 in primary monocytes." (PMID 34073784, 2021). "IL-6 can induce the polarization of primary T cells toward Th17 cells and promote neutrophil recruitment, thereby aggravating airway inflammation in asthma." (PMID 34402724, 2021). "In models of experimental asthma, the plasticity and loss of suppressive activities of nTregs from CD8−/− mice compared to WT mice was largely dependent on levels of IL-6 production." (PMID 33925531, 2021).
asthma (continued). "The inflammatory process also involves the synthesis of pro-inflammatory cytokines such as IL-1β, IL-6, TNFα, and TGFβ, which also contribute to asthma pathogenesis." (PMID 33418879, 2021). "Our inferences support further research into delineating the roles of IL-6 pathways in the asthma pathobiology and identifying patients with a distinct endotype who would benefit most from anti-IL-6 therapies." (PMID 33912579, 2021). "Plasma IL-6 was positively correlated with clinical features of metabolic dysfunction in more severe asthma." (PMID 34608825, 2021). "Our findings imply that ETV4 is involved in the pathogenesis of asthma, possibly through the heightened production of IL6." (PMID 34552174, 2021). "A more comprehensive understanding of the action mechanism of ZKPC on JAK2/STAT3 signaling pathway in human bronchial epithelial cells induced by IL-6 or M2 supernatant will enable ZKPC development in the control of asthma." (PMID 34608825, 2021). "Lastly, the endotype D was characterized by a low proportion of parental asthma and IgE sensitization, high abundance of M. catarrhalis, and high interleukin-6 (IL-6) response profile." (PMID 34127671, 2021). "Patients with asthma had significantly higher levels of IL-1β (19.74±16.77 vs. 2.63±5.22 pg/mL), IL-6 (7.55±8.65 vs. 2.37±2.47 pg/mL), and tumor necrosis factor-α (12.70±12.03 vs. 4.82±3.97 pg/mL) compared with the controls." (PMID 33503170, 2021). "Neutrophils are the main source of IL-6 generated in the airways of subjects with asthma, and increased levels of IL-6 have been found in asthmatic patients, although the association between IL-6 and severe asthma has only been demonstrated in adults." (PMID 34835964, 2021). "In this study, for the first time, we found that CCL21 levels in patients with asthma were lower than those in healthy controls, and the levels of IL-1β, IL-6, and TNF-α were higher in patients with asthma than in healthy controls." (PMID 33503170, 2021). "IL-37 attenuated the development of IL-1β, IL-6, and TNF-α in sputum cells (LPS-stimulated) in asthma patients and caused suppression of IL-17 production more notably in patients with asthma than in healthy controls." (PMID 34516405, 2021). "In all patients with asthma, the TNFα, IL-6 and sTNF RI levels were elevated compared to the control group." (PMID 34112152, 2021). "IL-6 has also emerged as a pivotal factor in the pathogenesis of asthma, a heterogeneous syndrome involving complex pathophysiological pathways." (PMID 33925531, 2021). "In turn, elevated serum IL-6 in asthmatics stays in line with the previous reports of persistent low-grade systemic inflammation in asthma." (PMID 32685129, 2020). "Nevertheless, these experiments using cells from asthma patients confirm the potential anti-inflammatory advantages of combining these drug classes, with an additive effect observed on IL-6 production." (PMID 31974640, 2020). "Consistent with the results of Th cell subset in mice, the asthma group displayed higher levels of IL-4, IL-17, IL-6, and TGF-β mRNA expression and lower levels of IFN-γ and IL-10 mRNA in the splenocytes than the normal and PBS groups." (PMID 32549755, 2020). "Especially, IL-6-mediated JAK/STAT3 signaling has been proven to play crucial roles in the airway remodeling of asthma." (PMID 33374928, 2020). "Nevertheless, there are several mucosal molecules/pathways that are currently under investigation as potential therapeutic targets for type 2 low or mixed type of asthma, these include IL‐6 and TLR‐3,4,7." (PMID 33133517, 2020). "Nonetheless, elevation of IL-6 is also correlated with elevated level of IL-13 and increased in asthma patients." (PMID 32624703, 2020). "The ability of regulating Th1 and Th2 differentiation makes IL-6 become a crucial factor in the onset of asthma." (PMID 32929606, 2020).
asthma (continued). "IL-6 is not only a proinflammatory cytokine but also an important biomarker for the evaluation of cancer, acute cellular rejection, pneumonia, asthma, and bacteremia." (PMID 32451375, 2020). "A study on cytokines in bronchoalveolar lavage fluid reported that patients with active asthma had increased TNF-α and IL-6 levels than healthy controls and stabilized patients with asthma." (PMID 32999682, 2020). "As inflammation is widely associated with asthma symptoms, we measured the inflammatory indicators in BALF, including IL-1β, IL-6, TNF-α, TGF-β, and IFN-γ." (PMID 33456673, 2020). "Asthma individuals were characterized by increased serum levels of IL-6, IL-10, alanine aminotransferase activity, as well as elevated monocyte, eosinophil, lymphocyte, and total white blood cell (WBC) counts as compared to controls." (PMID 32685129, 2020). "TNF-α and IL-6, highly expressed in the asthmatic subjects, are important pro-inflammatory cytokines in regulating asthma pathophysiology." (PMID 32929606, 2020). "Viral infection, including HRV infection, increases IL-6 levels in the respiratory tract, which correlates with airway remodeling and the severity of asthma." (PMID 32823491, 2020). "As it has been demonstrated, IL-6 and IL-12p70 were above the detection threshold in the majority of asthma patients." (PMID 32685129, 2020). "Studies have shown that the level of IL-6 is increased in various inflammatory diseases, including allergies, asthma, and autoimmune disease." (PMID 32887408, 2020). "There was an increased plasma expression of IL-10 and IL-6 in asthma and of c-x-c motif chemokine ligand 2 (CXCL2) and adrenomedullin (ADM) in pulmonary TB." (PMID 33023021, 2020). "An additional study demonstrated decreased expression of miR-18a, -27a, -128 and -155 in HBECs derived from individuals with asthma, and further knockdown of these miRNAs led to increased expression of the proinflammatory cytokines IL-6 and CXCL8." (PMID 33255348, 2020). "To demonstrate the potential of our approach in guiding the clinical care of patients, we first collected BALF samples from patients with asthma, and found that these samples are enriched in GN bacteria and IL-6 compared with healthy control individuals." (PMID 32451375, 2020). "All inhalations also decreased the levels of IL-6 in lung tissue and BALF, cytokine released by macrophages, found in the sputum of asthmatics and associated with asthma airway inflammation." (PMID 32645931, 2020). "The level of sCD93 which has potential role to predict asthma significantly increased after HDM stimulation via IL-6 and TSLP in vitro and in vivo." (PMID 31941986, 2020). "Another study indicated that the activation of STAT3 was higher in mild asthma, and IL-6 stimulation increased STAT3 phosphorylation." (PMID 31924195, 2020). "The levels of inflammatory factors including C-reactive protein (CRP), tumor necrosis factor-alpha (TNF-α), and interleukin-6 (IL-6) in peripheral serum of children with asthma were significantly higher than those in the controls." (PMID 32158441, 2020). "We use our method to characterize bronchoalveolar lavage fluid from patients with asthma, and find elevated GN bacteria and IL-6 levels compared to healthy subjects." (PMID 32451375, 2020). "It has been widely accepted that inflammatory cells, such as eosinophils and mast cells, as well as various cytokines, including TNF-α and IL-6, take part in the airway inflammatory response of asthma." (PMID 32929606, 2020). "MicroRNAs are known to regulate important pathways in asthma pathology including the IL-6 and IFN pathways." (PMID 31684064, 2019). "Group 1 consists of an anti-TSLP antibody, anti-IL-33R antibody, anti-IL-33R antibody, anti-IL-25 antibody, and anti-IL-6 antibody, which are investigational drugs for asthma." (PMID 31284537, 2019). "Of note, higher amounts of IL-6 have been found in patients with asthma and have been shown to trigger or to reinforce premature cellular senescence." (PMID 31849968, 2019).